FH (fumarate hydratase)
Description:
Catalyzes the reversible stereospecific interconversion of fumarate to L-malate. Experiments in other species have demonstrated that specific isoforms of this protein act in defined pathways and favor one direction over the other (Probable). [Isoform Mitochondrial]: Catalyzes the hydration of fumarate to L-malate in the tricarboxylic acid (TCA) cycle to facilitate a transition step in the production of energy in the form of NADH. [Isoform Cytoplasmic]: Catalyzes the dehydration of L-malate to fumarate (By similarity). Fumarate metabolism in the cytosol plays a role during urea cycle and arginine metabolism; fumarate being a by-product of the urea cycle and amino-acid catabolism (By similarity). Also plays a role in DNA repair by promoting non-homologous end-joining (NHEJ). In response to DNA damage and phosphorylation by PRKDC, translocates to the nucleus and accumulates at DNA double-strand breaks (DSBs): acts by catalyzing formation of fumarate, an inhibitor of KDM2B histone demethylase activity, resulting in enhanced dimethylation of histone H3 'Lys-36' (H3K36me2).
Synonyms: HsFH; FMRD; HLRCC; LRCC; MCL; MCUL1
Tractability: Small molecule: a structure with a bound ligand is known; it has a binding pocket of medium quality. PROTAC: ubiquitination databases record sites on it; its protein half-life has been measured.
Target class: Enzyme; Lyase
Gene: Protein-coding gene on chromosome 1 (241,497,511 to 241,519,799, reverse strand). Ensembl gene ENSG00000091483.
Subcellular location: Mitochondrion (Isoform Mitochondrial); Cytoplasm, cytosol (Isoform Cytoplasmic); Nucleus; Chromosome
Subcellular location (Human Protein Atlas): Mitochondria
Pathways (Reactome):
Metabolism: Citric acid cycle (TCA cycle)
Metabolism of proteins: Mitochondrial protein degradation
Gene Ontology:
Molecular function: fumarate hydratase activity; protein binding; catalytic activity; lyase activity
Biological process: fumarate metabolic process; malate metabolic process; arginine metabolic process; positive regulation of cold-induced thermogenesis; tricarboxylic acid cycle; urea cycle
Cellular component: chromosome; cytosol; extracellular exosome; mitochondrion; nucleus; cytoplasm; mitochondrial matrix
Genetic constraint (gnomAD): Loss-of-function variants: 20 observed, 48.54 expected, observed/expected ratio (o/e) 0.41, 90% interval 0.29 to 0.6. The upper end of that interval is the gene's LOEUF score, 0.6, which puts it in group 2 of 6, group 1 being the genes least tolerant of losing a copy. Missense variants: 523 observed, 669.84 expected, observed/expected ratio (o/e) 0.78, 90% interval 0.73 to 0.84. Synonymous variants: 208 observed, 232.02 expected, observed/expected ratio (o/e) 0.9, 90% interval 0.8 to 1.01.
Gene-disease validity (ClinGen):
ClinGen rates the evidence that FH causes each of these diseases.
hereditary leiomyomatosis and renal cell cancer (autosomal dominant): Definitive. Hereditary leiomyomatosis and renal cell cancer (HLRCC) is a hereditary cancer syndrome characterized by a predisposition to cutaneous and uterine leiomyomas and, in some families, to renal cell cancer.
Cancer hallmarks: change of cellular energetics; escaping immune response to cancer (suppresses); genome instability and mutations; genome instability and mutations (suppresses); angiogenesis; escaping programmed cell death (suppresses); invasion and metastasis (suppresses); suppression of growth (promotes)
Homologues: Orthologues: chimpanzee FH (99% identical), macaque FH (99% identical), dog FH (95% identical), guinea pig FH (95% identical), pig FH (95% identical), rat Fh (93% identical), mouse Fh1 (93% identical), zebrafish fh (82% identical), tropical clawed frog map1lc3c (81% identical), Drosophila melanogaster Fum1 (71% identical), Caenorhabditis elegans fum-1 (70% identical), Drosophila melanogaster Fum2 (68% identical), and 3 more. Paralogues in human: ASL (18% identical), ADSL (18% identical).
Diseases named in the same sentence as FH in open-access papers:
FH is named in the same sentence as 255 diseases in open-access papers, as found by Europe PMC text mining. Sharing a sentence is not in itself a finding about the gene and the disease. The quoted sentences say what the papers report.
hereditary leiomyomatosis and renal cell cancer (201 papers, 2006 to 2026). "Fumarate hydratase-deficient renal cell carcinoma is a rare type of renal cell carcinoma often associated with hereditary leiomyomatosis and renal cell carcinoma syndrome." (PMID 41789002, 2026). "Hereditary leiomyomatosis renal cell carcinoma (HLRCC) is caused by Fumarate Hydratase (FH) mutations, leading to aggressive tumors." (PMID 40649942, 2025). "Genetic analysis using DNA extracted from normal kidney tissues in surgical specimens (blood sample absence) confirmed the FH mutation, and hereditary leiomyomatosis and renal cell cancer was diagnosed posthumously." (PMID 40034895, 2025). "This subtype of leiomyoma can occur sporadically due to a somatic mutation in the fumarate hydratase (FH) gene, while FH mutations in the germline are associated with hereditary leiomyomatosis and renal cell carcinoma syndrome (HLRCC)." (PMID 41374387, 2025). "The basic alteration of hereditary leiomyomatosis is the germline heterozygous variant of the FH gene, and loss-of-heterozygosity at this locus cause the complete loss of enzyme function of fumarate hydratase in the tumor tissue." (PMID 40264827, 2025). "Mutations in the gene encoding fumarate hydratase (FH) can lead to profound cellular metabolic alterations and fumarate accumulation, which can predispose to hereditary leiomyomatosis and renal cell cancer syndrome." (PMID 40999586, 2025). "Hereditary leiomyomatosis and renal cell cancer is an autosomal dominant disorder caused by germline mutations in the FH gene and is associated with poor prognosis of aggressive renal cancer." (PMID 40034895, 2025). "FH-deficient RCC, frequently linked to hereditary leiomyomatosis, is driven by fumarate hydratase inactivation, leading to HIF accumulation and VEGF upregulation, which underscores its aggressive nature and potential responsiveness to specific strategies." (PMID 41294834, 2025). "Mutations in the FH gene have been identified in various types of tumors, including hereditary leiomyomatosis and renal cell carcinoma (HLRCC), a condition characterized by the development of multiple benign and malignant tumors." (PMID 40002168, 2025). "Hereditary leiomyomatosis and renal cell cancer syndrome is a rare autosomal dominant disease caused by mutations in the fumarate hydratase gene." (PMID 38784227, 2024). "FH deficiency occurs both in sporadic mutations within leiomyomas, as well as somatic mutations in hereditary leiomyomatosis and renal cell carcinoma (HLRCC) which is characterized by heterozygous germline mutations in FH." (PMID 38957794, 2024). "Hereditary leiomyomatosis and renal cell cancer (HLRCC) is a rare autosomal dominant inheritable disease caused by Fumarate hydratase (FH) gene germline mutation." (PMID 38933105, 2024). "Hereditary leiomyomatosis and renal cell carcinoma (HLRCC) is a kind of more aggressive RCC with germline loss-of-function mutation of FH." (PMID 38374146, 2024). "In hereditary leiomyomatosis and renal cell carcinoma syndrome, fumarate hydratase–deficient renal cell carcinomas typically present as aggressive, unilateral, often cystic masses with heterogeneous enhancement." (PMID 39282017, 2024). "Hereditary leiomyomatosis and renal cell cancer (HLRCC) is an autosomal dominant inherited disease that originates from germ-line mutations in the fumarate hydratase (FH) gene." (PMID 39021564, 2024). "Herein, we demonstrate a pathogenic germline variant of the fumarate hydratase gene in a 60-year-old woman with multiple cutaneous leiomyomas, leading to the diagnosis of hereditary leiomyomatosis and renal cell cancer." (PMID 38928693, 2024). "Fumarate hydratase is an oncoenzyme, whose loss is associated with hereditary leiomyomatosis and renal cell cancer (HLRCC)." (PMID 38521964, 2024).
hereditary leiomyomatosis and renal cell cancer (continued). "The majority of FH-d ULs are sporadic, caused by somatic FH inactivation, while a minority of cases occur in the context of the hereditary leiomyomatosis and renal cell carcinoma (HLRCC) syndrome caused by germline FH inactivation." (PMID 38642139, 2024). "Immunostaining for FH and 2SC is widely used to detect FH deficiency caused by germline FH mutations in hereditary leiomyomatosis and renal cell carcinoma syndrome." (PMID 38721148, 2024). "Hereditary leiomyomatosis and renal cell cancer (HLRCC) is a rare autosomal-dominant disorder caused by a heterozygous germline mutation in the fumarate hydratase (FH) gene." (PMID 39184870, 2024). "FH mutation results in the accumulation of fumarate and is associated with human cancers, including hereditary leiomyomatosis and renal cell cancer." (PMID 37016705, 2023). "In the fifth edition of the WHO cancer classification, FH-deficient RCC has replaced hereditary leiomyomatosis and renal cell carcinoma (HLRCC) as a separate molecular subtype." (PMID 37367052, 2023). "Frequently referred to as the HLRCC syndrome (Hereditary Leiomyomatosis and Renal Cell Carcinoma), Reed’s syndrome is caused by germline mutations in FH, the gene encoding fumarate hydratase, a tricarboxylic acid cycle enzyme." (PMID 36982825, 2023). "Some studies have found that 2SC is a biomarker for not only mitochondrial stress in obesity and diabetes, but also fumarate hydratase (FH) deficiency in individuals with hereditary leiomyomatosis and renal cell carcinoma (HLRCC)." (PMID 37795435, 2023). "FH-deficient RCC is a disease associated with hereditary leiomyomatosis and renal cell carcinoma (HLRCC), which manifests as cutaneous or uterine leiomyomas with or without aggressive RCC." (PMID 37053010, 2023). "Heterozygous carriers of FH mutations have increased risk of developing uterine fibroids that can be associated with hereditary leiomyomatosis and renal cell cancer (HLRCC)." (PMID 37663422, 2023). "Germline mutations of FH lead to hereditary leiomyomatosis and renal cell carcinoma (HLRCC), a cancer syndrome characterized by a highly aggressive form of renal cancer." (PMID 36269833, 2022). "Germline FH mutations result in Hereditary Leiomyomatosis and Renal Cell Cancer (HLRCC) syndrome, characterized by cutaneous and uterine leiomyomas and renal cell carcinomas with unique nucleolar features." (PMID 36128328, 2022). "Hereditary leiomyomatosis and renal cell carcinoma caused by loss-of-function germline variants of the FH gene can develop into aggressive renal cell carcinoma (RCC)." (PMID 35034951, 2022). "Loss-of-function variants, including splicing variants in the FH gene, have been associated with hereditary leiomyomatosis and renal cell cancer (HLRCC) syndrome." (PMID 35806449, 2022). "In hereditary papillary renal carcinoma (mutation in MET, 7q31.2) and hereditary leiomyomatosis and renal cell cancer (mutation in fumarate hydratase, FH, 1q43) the main histotype of kidney cancer is papillary RCC (pRCC), type 1 and type 2, respectively." (PMID 34572815, 2021). "The fumarate hydratase gene (FH) was discovered to bear an N64T mutation in an individual with a Leydig cell tumor who was part of a kindred with hereditary leiomyomatosis and renal cell cancer (HLRCC)." (PMID 34200553, 2021). "Among the FH mutations, the missense and frameshift are the most common found in uterine fibroids, hereditary leiomyomatosis, and renal cell carcinoma syndrome (HLRCC) and also in PGLs and PCCs." (PMID 34070384, 2021). "Hereditary leiomyomatosis and renal cell carcinoma is an uncommon autosomal dominant disease caused by mutations in the fumarate hydratase (FH) gene." (PMID 34889279, 2021). "Further, mutations in another TCA cycle enzyme, fumarate hydratase (FH), cause hereditary leiomyomatosis and renal cell cancer." (PMID 33673109, 2021).
hereditary leiomyomatosis and renal cell cancer (continued). "Hereditary leiomyomatosis and renal cell carcinoma (HLRCC) syndrome is believed to result from an autosomal dominant mutation in the fumarate hydratase (FH) gene on chromosome 1." (PMID 33747650, 2021). "Hereditary leiomyomatosis and renal cell carcinoma (HLRCC) is an aggressive form of RCC characterized by germline inactivating mutation of fumarate hydratase (FH), followed by somatic loss of the remaining wild-type allele." (PMID 32774853, 2020). "The fumarate hydratase (FH) deficient subtype is found in up to 1.6% and can occur in hereditary leiomyomatosis and renal cell carcinoma (HLRCC) syndrome." (PMID 32612247, 2020). "The majority of FH-RCC cases are associated with germline FH mutations as part of the hereditary leiomyomatosis and renal cell carcinoma (HLRCC) syndrome characterized by cutaneous and uterine leiomyomas and increased risk of FH-RCC." (PMID 32197306, 2020). "The loss-of-function mutation of fumarate hydratase (FH) is a driver of hereditary leiomyomatosis and renal cell carcinoma (HLRCC)." (PMID 32774853, 2020). "Germline Loss-of-Function variants (both truncating and missense) in the fumarate hydratase (FH) (fumarase) gene FH cause the dominantly inherited hereditary leiomyomatosis and renal cell cancer syndrome (HLRCC; OMIM #150800)." (PMID 32612247, 2020). "Hereditary leiomyomatosis and renal cell cancer (HLRCC) is an autosomal dominant syndrome caused by heterozygous germline variants in the fumarate hydratase (FH) gene, associated with an increased risk of developing renal cell carcinoma (RCC)." (PMID 31792767, 2020). "Heterozygous germline mutations of fumarate hydratase (FH) predispose for hereditary leiomyomatosis and renal cell carcinoma." (PMID 32994210, 2020). "Germline mutations in fumarate hydratase (FH), which is responsible for the conversion of fumarate to malate, results in the accumulation of fumarate in patients with hereditary leiomyomatosis RCC (HLRCC)." (PMID 30736384, 2019). "Hereditary leiomyomatosis and renal cell carcinoma (HLRCC) syndrome is a rare autosomal-dominant hereditary syndrome caused by germline mutation in the fumarate hydratase (FH) gene." (PMID 31182090, 2019). "FH is a tricarboxylic acid cycle enzyme that converts fumarate to malate, and inactivating mutations in FH are associated with the highly malignant hereditary leiomyomatosis and renal cell cancer." (PMID 29679077, 2018). "Patients with RCC associated with hereditary leiomyomatosis and renal cancer syndrome have an autosomal dominant inherited germline mutation in the FH gene on chromosome 1 that encodes for fumarate hydratase." (PMID 30123932, 2018). "Germline mutations in FH have previously been reported in FH-deficiency syndrome, multiple cutaneous and uterine leiomyomatosis, hereditary leiomyomatosis and renal cancer, and neuroblastoma." (PMID 30062063, 2018). "The clinical spectrum associated with hereditary leiomyomatosis and renal cell carcinoma syndrome (associated with FH mutations) was assessed in 182 cases from 114 families and found only two cases of PPGL." (PMID 29794126, 2018). "Hereditary leiomyomatosis and renal cell cancer is caused by monoallelic FH mutations that lead to reduced activity of the enzyme fumarate hydratase." (PMID 29552546, 2018). "Heterozygous germline mutations in the FH gene predispose to an aggressive autosomal dominant inherited early-onset kidney cancer syndrome: hereditary leiomyomatosis and renal cell cancer (HLRCC)." (PMID 28747166, 2017). "Autosomal dominant mutations in FH are associated with hereditary leiomyomatosis and renal cell cancer, indicating that FH functions as a tumor suppressor." (PMID 28202494, 2017). "Heterozygous mutations of FH are responsible for atypical uterine leiomyomas, hereditary leiomyomatosis and renal cell cancer." (PMID 27556703, 2016).
hereditary leiomyomatosis and renal cell cancer (continued). "A clinic study shows that the mutation of FH gene results in the Reed syndrome, which is an autosomal dominant disorder characterized by cutaneous leiomyomas, uterine leiomyomas, and renal cell carcinoma, possibly representing genetic heritage lesions." (PMID 27556703, 2016). "Like SDH mutations, FH mutations significantly reduce FH activity, resulting in the accumulation of fumarate to a level as high as 417–688 μmol/g protein in hereditary leiomyomatosis and renal cell cancer." (PMID 26812134, 2016). "Here, we perform a high-throughput RNAi screen to identify synthetic lethal genes with fumarate hydratase (FH), a metabolic tumor suppressor whose loss-of-function has been associated with hereditary leiomyomatosis and renal cell carcinoma (HLRCC)." (PMID 24568598, 2014). "Inherited mutations in the Krebs cycle enzyme fumarate hydratase (FH) predispose to hereditary leiomyomatosis and renal cell cancer (HLRCC)." (PMID 25105836, 2014). "The definitive diagnosis of Reed syndrome can be made by detecting a mutation in the FH gene upon sequencing or by detecting decreased enzyme activity." (PMID 23935639, 2013). "Mutations in one of these enzymes, fumarate hydratase (FH), predispose individuals to hereditary leiomyomatosis and renal cell cancer (HLRCC)." (PMID 23643539, 2013). "The gene encoding the Krebs cycle enzyme fumarate hydratase (FH) is mutated in hereditary leiomyomatosis and renal cell cancer (HLRCC)." (PMID 23499446, 2013). "Mutations in the genes coding for SDH subunits B, C and D predispose to familial paragangliomas and phaeochromocytomas, and mutations in FH cause hereditary leiomyomatosis and renal cell carcinomas." (PMID 19778456, 2009). "Similarly, the accumulation of fumarate, due to fumarate hydratase (FH) mutations, happens in hereditary leiomyomatosis and renal cell carcinoma." (PMID 39684900, 2024). "Mutations that lead to FH inactivation can give rise to two distinct disorders: fumarate hydratase deficiency, an autosomal recessive disorder of metabolism, and hereditary leiomyomatosis and renal cell carcinoma (HLRCC), an autosomal dominant cancer syndrome with incomplete penetrance." (PMID 38793008, 2024). "Among familial RCC syndromes, the fumarate hydratase (FH) germline mutation that interferes with the function of the Krebs cycle has been highlighted, causing hereditary leiomyomatosis and renal cell cancer (HLRCC) and being associated with an aggressive form of papillary RCC (pRCC)." (PMID 37754269, 2023). "Hereditary leiomyomatosis and renal cell carcinoma (HLRCC) is a rare familial cancer syndrome with an autosomal dominant pattern of inheritance characterized by germline mutations in the TCA cycle enzyme fumarate hydratase (FH)." (PMID 37259915, 2023). "Fibroids may also harbour germline mutations of the FH, which encodes the tricarboxylic cycle enzyme fumarase, predisposing women to the hereditary leiomyomatosis and renal cell cancer (HLRCC) syndrome." (PMID 37113812, 2023). "Considering that, in some cases, the diagnosis of leiomyomas can also imply specific and underlying genetic mutations (e.g., fumarate hydratase (FH) mutation in hereditary leiomyomatosis with renal cell carcinoma (RCC)), their rapid recognition by the clinicians is of primary importance." (PMID 36557047, 2022). "Homozygous mutations in the FH gene have previously been reported to cause a severe neurological disorder, and heterozygous germline mutations in the FH gene result in a clinical syndrome characterized by hereditary leiomyomatosis and renal cell cancer." (PMID 30668541, 2019). "Although FH is a tumor suppressor (i.e., FH mutations result in hereditary leiomyomatosis and renal-cell cancer) and fumarate is proposed to function as an oncometabolite, the role of FH in leukemic transformation remains unknown." (PMID 28202494, 2017).